PCSK9 (proprotein convertase subtilisin/kexin type 9)
Diseases named in the same sentence as PCSK9 in open-access papers (continued):
Sharing a sentence is not in itself a finding about the gene and the disease.
cardiovascular disease (continued). "We review success stories including PCSK9-related drugs in cardiovascular disease and evidence supporting the use of human genetics to guide drug discovery, while highlighting advances in artificial intelligence and machine learning with the potential to improve target discovery in skeletal biology." (PMID 40225702, 2025). "Proprotein convertase subtilisin/kexin type 9 (PCSK9) increases circulating LDL levels and cardiovascular disease (CVD) risk; its levels may be related to the dysregulation of glycemic control and may be affected by estrogens." (PMID 40144869, 2025). "In addition, this strategy opens avenues for future multi-target peptide-based therapies that combine Anti-PCSK9 peptides with other atheroprotective targets, potentially broadening the scope of cardiovascular disease prevention." (PMID 41012095, 2025). "Loss-of-function variants in PCSK9 are associated with lower levels of circulating low-density lipoprotein cholesterol (LDL-C) and reduced cardiovascular disease (CVD) risk, while gain-of-function variants correlate with elevated LDL-C concentrations and increased CVD risk." (PMID 41073127, 2025). "Collaboration and further research in this area may lead to the development of novel therapeutic interventions targeting PCSK9 to address age-related cardiovascular disorders and improve vascular health." (PMID 40354375, 2025). "Moreover, the suppression of PCSK9 using Alirocumab significantly decelerated the advancement of cardiovascular disease in aging rats, suggesting that PCSK9 is pivotal in cardiovascular aging." (PMID 40354375, 2025). "By analyzing these articles, we describe the major advancements in PCSK9 research regarding topics, institutions, countries, authors, and study types in cardiovascular disease research, offering researchers a quick understanding of the major research directions in this field." (PMID 38887452, 2024). "PCSK9 inhibitors like evolocumab and inclisiran have been shown to lower low-density lipoprotein cholesterol levels and to reduce the rate of cardiovascular events among patients with established cardiovascular disease accompanied with T2DM." (PMID 39493778, 2024). "The latest keyword outbreaks include proprotein convertase subtilisin, inflammation, bempedoic acid, and inclisiran, which could be potential frontiers in the field of cardiovascular disease and PCSK9 research." (PMID 38887452, 2024). "Some losses of function due to mutations in the PCSK9 gene are associated with almost pristine coronary arteries and no cardiovascular diseases even in advanced age." (PMID 37530998, 2024). "This indicates a direct involvement of PCSK9 in the pathogenesis of cardiovascular diseases." (PMID 38886277, 2024). "Involvement of PCSK9 has been investigated mainly in cardiovascular diseases (CVD)." (PMID 39138259, 2024). "Knowledge of these mechanisms may contribute to the wider use of PCSK9 inhibitors in the treatment of cardiovascular diseases." (PMID 38886277, 2024). "According to keyword timeline and burst analysis, it is evident that proprotein convertase subtilisin, inflammation, bempedoic acid, and inclisiran may emerge as new potential frontiers in cardiovascular diseases and PCSK9 research." (PMID 38887452, 2024). "Notably, there were relatively few connections between different groups, suggesting a lack of collaborations between research teams/laboratories in the researches related to cardiovascular diseases and PCSK9." (PMID 38887452, 2024). "PCSK9 inhibitors are recommended in primary prophylactic treatment for cardiovascular disease when the lipid target in accordance with cardiovascular risk is not achieved during treatment with statins at the highest tolerated dose or in secondary prevention to a cardiovascular event." (PMID 38509261, 2024).
cardiovascular disease (continued). "Additionally, the understanding of these functions and implications of PCSK9 can provide valuable insights into the pathophysiology of cardiovascular diseases and potential therapeutic targets for intervention." (PMID 38999903, 2024). "Previously, it was reported that gain-of-function mutations in PCSK9 resulted in autosomal dominant familial hypercholesterolemia, whereas loss-of-function mutations in PCSK9 reduced plasma LDL-C levels and decreased risk of cardiovascular disease (CVD)." (PMID 39628814, 2024). "However, it still lacks precise information on countries, authors, publications, institutions, journals, and keywords related to cardiovascular diseases and researches in the field of PCSK9." (PMID 38887452, 2024). "Serum PCSK9 was first demonstrated to be associated with cardiovascular disease (CVD) in a 60-year-old population without CVD, and even when established CVD risk variables were modulated, this association persisted." (PMID 38273837, 2023). "Thus, the purpose of our study is to examine the effect of PCSK9 inhibitors and siRNA therapies on major adverse cardiac events and degree of LDL reduction in patients with cardiovascular disease and those at high risk of cardiovascular disease." (PMID 38055686, 2023). "In recent years, the functional pleiotropy of PCSK9 has been gradually recognized, and its immunoregulatory function has attracted much attention, especially in the fields of autoimmune diseases, cancer, and cardiovascular diseases." (PMID 36970356, 2023). "•PCSK9 may emerge as a novel target and a potential biomarker for age-related cardiovascular disease." (PMID 38094682, 2023). "Finally, we propose several issues that need to be addressed in the future regarding PCSK9 and cardiovascular diseases." (PMID 36970356, 2023). "Apart from PCSK9, little is known about PCSKs in cardiovascular disease." (PMID 36188622, 2022). "Therefore, PCSK9 has been identified as a possible target for the development of innovative cardiovascular disease therapeutics." (PMID 36005422, 2022). "These discoveries regarding the relation of PCSK9 to inflammation have refreshed our understandings of the PCSK9 and PCSK9 inhibitors, which may help to promote a new era of cardiovascular disease prevention." (PMID 35252378, 2022). "Hence, several in vitro studies have been done to explore the potential roles of PCSK9 in platelet activation-induced cardiovascular disease, whereby almost purified human platelets were used as a model of study." (PMID 36005422, 2022). "While in vitro human or mouse platelet cultures combined with in vivo studies in mice or rabbits have been recently used for PCSK9 and platelet activation research, there have been various studies on PCSK9-related cardiovascular disease studies employing another in vitro and in vivo model." (PMID 36005422, 2022). "This suggests that PCSK9 may also influence vascular biology and the progression of cardiovascular disease through other mechanisms." (PMID 36230934, 2022). "Increased plasma protein PCSK9, which has been confirmed to be related to cardiovascular disease, may be mitigated by a small molecule by targeting the 80 s ribosome." (PMID 35050240, 2022). "PCSK9 can bind to TLRs, increase the levels of P-IκBα, IkBα degradation, and NF-κB nuclear translocation in macrophages, regulate the microenvironment of myocardial inflammation, and influence the course of cardiovascular disease." (PMID 36230934, 2022).
cardiovascular disease (continued). "While mice models have been commonly used for PCSK9-induced cardiovascular disease in vivo studies, they have limitations because they lack the central features of human cardiovascular pathophysiology, clinical manifestations, and some intravascular procedures for imaging." (PMID 36005422, 2022). "Despite PCSK9 has been studied mostly in cardiovascular diseases, it also participates in general mechanisms shared by many other diseases, and hence it is conceivable that PCSK9 is involved in the initiation and progression of other pathologies with powerful inflammatory or thrombotic components." (PMID 33834043, 2021). "Understanding both environmental and genetic predictors of PCSK9 levels may help identify new targets for cardiovascular disease treatment and contribute to a better assessment of the benefits of long-term PCSK9 inhibition." (PMID 34659352, 2021). "In this review, we summarize the general information regarding (i) the role of LDL-C in atherosclerotic cardiovascular disease, (ii) data regarding the role of PCSK9 in cholesterol metabolism, (iii) pleiotropic effects of PCSK9, and (iv) the effects of PCSK9 silencing." (PMID 34199468, 2021). "Proprotein convertase subtilisin/kexin type 9 (PCSK9) is a key factor in several cardiovascular diseases, as it is responsible for the elevation of circulating low-density lipoprotein cholesterol (LDL-C) levels in blood plasma by direct interaction with the LDL receptor." (PMID 33801308, 2021). "Inhibitory monoclonal PCSK9 antibodies did not reduce highly sensitive CRP levels in patients with an increased risk for cardiovascular diseases." (PMID 33920491, 2021). "However, we did observe an adverse effect of PCSK9 inhibition on OC and OPC risk, which was of a similar magnitude to the protective effect seen in relation to cardiovascular disease using the same genetic instrument." (PMID 33886544, 2021). "Understanding both environmental and genetic predictors of PCSK9 levels may help identify new targets for cardiovascular disease treatment and contribute to better assessment of the benefits of long-term PCSK9 inhibition." (PMID 34659352, 2021). "So-called statins (HMG-CoA reductase inhibitors) and proprotein convertase subtilisin/kexin type 9 (PCSK-9) inhibitors to reduce LDL-C by approximately half at maximum are used for the purpose of preventing arteriosclerotic diseases including cardiovascular disease (CVD)." (PMID 33610176, 2021). "Additionally, PCSK9 concentrations were also observed to be significantly correlated with hs-CRP (high sensitivity C-reactive protein) in patients with the existence of cardiovascular disease." (PMID 32456228, 2020). "Furthermore we found that oxLDL, which also plays a pivotal role in the pathophysiology of cardiovascular disease, impaired cardiomyocyte function in a PCSK9-dependent way." (PMID 33169229, 2020). "Therefore, PCSK9 is a highly attractive potential target, and future studies will further show the full potential of ASO-based PCSK9 inhibition in preventing cardiovascular diseases." (PMID 32034521, 2020). "For this reason, PCSK9 genetic gain-of-function (GOF) mutations are associated to hypercholesterolemic conditions, and its pharmacological inhibition has been considered as a new line of intervention for preventing cardiovascular diseases." (PMID 32429343, 2020). "For this reason, ANGPTL3 is considered an important new pharmacological target for the treatment of cardiovascular diseases (CVDs) together with more conventional lipid lowering therapies, such as statins and anti proprotein convertase subtilisin/kexin type 9 (PCSK9) monoclonal antibodies." (PMID 30011918, 2018).
cardiovascular disease (continued). "Heart transplant recipients, due to higher primary cardiovascular disease risk (with 90% having ASCVD ≥7.5%), may be more responsive to PCSK9 inhibitors, while liver transplant recipients exhibited lower risk (60%), which may be related to metabolic differences." (PMID 40918505, 2025). "In addition, most of the included trials enrolled stable cardiovascular disease patients with relatively low SCD risk, which may have attenuated the potential antiarrhythmic effects of PCSK9 inhibitors therapy." (PMID 40779566, 2025). "This work provides valuable insights into the design of small-molecule inhibitors targeting PCSK9, establishing a foundation for subsequent experimental validation and optimization of these compounds for the treatment of hyperlipidemia and related cardiovascular diseases." (PMID 40733228, 2025). "Notably, another MR study failed to establish a relationship between PCSK9 and HF in patients with non-ischemic cardiovascular disease (CVD) events, leaving the association between PCSK9 and ischemic HF uncertain." (PMID 38383373, 2024). "The accurate measurement of Low-density lipoprotein cholesterol (LDL-C) is critical in the decision to utilize the new lipid-lowering therapies like PCSK9-inhibitors (PCSK9i) for high-risk cardiovascular disease patients that do not achieve sufficiently low LDL-C on statin therapy." (PMID 38331834, 2024). "As the landscape of PCSK9 inhibition continues to evolve, our study provides critical insights that could inform the development of more effective and safe therapeutic strategies for patients with cardiovascular disease." (PMID 39906341, 2024). "The proprotein convertase subtilisin kexin 9 (PCSK9) inhibits the uptake of low-density lipoproteins (LDLs), which contain lipids, into the liver and may thus be associated with nonalcoholic fatty liver disease (NAFLD), a cardiovascular disorder (CVD) risk." (PMID 39519519, 2024). "However, these researches of sex-related PCSK9 mainly focused on cardiovascular diseases." (PMID 37860186, 2023). "With the expanding prevalence of CAD and the increasingly widespread use of PCSK9 inhibitors (e.g., Evolocumab and Alirocumab) to reduce cardiovascular risk, accurate assessment of LDL-C levels is becoming more crucial for the secondary prevention of cardiovascular disease." (PMID 36286294, 2022). "The updated AIFA rules for PCSK9 inhibitors reimbursement increase the number of patients who could benefit from this treatment by 14.4%, including more patients in secondary prevention for cardiovascular diseases." (PMID 36012937, 2022). "In addition, sex differences have reportedly appeared in PCSK9 levels and cardiovascular diseases." (PMID 34996457, 2022). "As expected, PCSK9 “genetic inhibition” may target aging‐associated diseases through its association with lifelong exposure to low LDL cholesterol levels and associated reduction in the risk of cardiovascular diseases." (PMID 34704651, 2021). "In this study, the correlation between apo C3 and PCSK9 concentrations was observed in the whole group of DM2 patients as well as in patients with NAFLD only, which might support the role of PCSK9 and apo C3 in the pathogenesis of cardiovascular disease in NAFLD diabetic patients." (PMID 35024053, 2021).
cardiovascular disease (continued). "Moreover, based on our study, elevated circulating PCSK9 levels may emerge as novel target of efficacious prevention of cardiovascular disease in women." (PMID 34041285, 2021). "This suggests that interventions such as siRNA, anti-sense RNA, ribozymes, or gene editing, that are targeted at PCSK9 gene expression in the liver might benefit cardiovascular disease even more than can be achieved by administration of PCSK9 monoclonal antibodies." (PMID 29180444, 2018). "Pcsk9 encodes an enzyme that regulates low-density lipoprotein (LDL) receptor degradation, and loss-of-function mutations in Pcsk9 are associated with low serum cholesterol levels and reduced risk of cardiovascular disease with no recorded adverse side effects." (PMID 29700298, 2018). "Barely a decade after the discovery of the gene encoding proprotein convertase subtilisin/kexin type 9 (PCSK9) and its recognition as a key player in cholesterol metabolism, PCSK9 inhibition is now considered an exciting approach in the reduction of residual risk of cardiovascular disease." (PMID 26456772, 2015). "Thus, it is evident that PCSK9 inhibitors not only effectively lower LDL-C but may also reduce the occurrence of cardiovascular events in high-risk patients, demonstrating their potential in the prevention of cardiovascular diseases." (PMID 41478627, 2025). "PCSK9 inhibitors have been shown to lower serum low density lipoprotein cholesterol (LDL-C) levels and are considered integral in the treatment of cardiovascular diseases." (PMID 38789568, 2024). "PCSK9 inhibitors have however been observed to decrease the rates of cardiovascular events in genetic CVD models and in patients with known cardiovascular disease." (PMID 39766777, 2024). "Several trials found that evolocumab, a PCSK9 inhibitor, can significantly lower LDL levels and cardiovascular disease risk." (PMID 39025905, 2024). "Passive immunization utilizing anti-PCSK9 antibodies, including alirocumab and evolocumab, has demonstrated notable efficacy in decreasing LDL-C levels and ameliorating cardiovascular disease." (PMID 38999903, 2024). "Various therapies aimed at increasing the amount of LDLRs, such as statins and antibodies against proprotein convertase subtilisin/kexin type 9 (PCSK9), are effective in reducing cardiovascular disease incidence." (PMID 38556050, 2024). "In summary, PCSK9 inhibitors significantly reduce the level of LDL-C, and the development of related drugs is of great significance for the treatment of cardiovascular diseases." (PMID 36230934, 2022). "PCSK9 inhibition or silencing is presently used in clinics worldwide to reduce LDL-cholesterol, resulting in lower incidence of cardiovascular disease and possibly cancer/metastasis." (PMID 36566984, 2022). "Monoclonal antibody PCSK9 inhibitors demonstrated remarkable efficacy in the general population in reducing LDL cholesterol levels and preventing cardiovascular disease." (PMID 35683632, 2022). "In the case of cardiovascular disease, CRISPR gene editing can greatly reduce serum levels of PCSK9 and total cholesterol by targeting the PCSK9 gene in hepatocytes in vivo." (PMID 31124015, 2019). "Monoclonal antibody inhibition of proprotein convertase subtilisin-kexin type 9 (PCSK9), which reduces LDL cholesterol by about 60% via reducing LDL receptor degradation, improves clinical outcomes in patients with cardiovascular disease." (PMID 30283400, 2018). "CRISPR/Cas9 gene editing of the loss-of-function proprotein convertase subtilisin/kexin type 9 (PCSK9) has also proven to reduce LDL cholesterol levels and protect against cardiovascular disease." (PMID 30086710, 2018).